MMP2 (matrix metallopeptidase 2)
Diseases named in the same sentence as MMP2 in open-access papers (continued):
Sharing a sentence is not in itself a finding about the gene and the disease.
tumor (continued). "This pathway can also regulate the expression of MMP‐2 and MMP‐9, which not only degrades the ECM, enhances the aggressiveness of tumor cells, but also maintains the microenvironment of tumor growth." (PMID 32786144, 2020). "Hypoxia has been shown to induce the expression of MMP2 and MMP9, which are important molecules for tumor cell invasion and metastasis." (PMID 32993787, 2020). "MMP-2, MMP-7, MMP-9, and MMP-12 belong to metalloproteinases (MMPs), a family of zinc-binding enzymes related to tumor invasion and angiogenesis." (PMID 33113766, 2020). "DOX and T. pratense extract synergistically down‐regulated MMP‐2 and up‐regulated SIRT‐1 genes, decreased the number of CK5/6‐positive cells in tumor tissues, and inhibited metastasis of GATA‐3‐positive cells into the lung and brain." (PMID 33133558, 2020). "Further study revealed that Twist1 binds to the promoters of MMP-2 and MMP-14 genes to regulate the tumor-suppressive effects of miR-539-5p." (PMID 32169087, 2020). "AEBR reduces matrix metalloproteinase 2 (MMP2), matrix metalloproteinase 9 (MMP9), and urokinase plasminogen activator (uPA) expression in mouse tumor tissues and also restrains VEGF activity and thus angiogenesis in the tumor tissue." (PMID 32665895, 2020). "Doxycycline treatment downregulated the levels of MMP-2, MMP-8, MMP-9 and NF-kB in a dose-dependent manner, which represents another important molecular pattern that restricts tumour cell proliferation, invasion and angiogenesis." (PMID 32377334, 2020). "Among them, MMP-2 and MMP-9 are of particular importance for the development of enzyme-responsive anti-tumor drug delivery systems due to their proved correlation with cancer cell invasion and metastasis formation." (PMID 32850662, 2020). "Upon encountering the weakly acidic microenvironment at the tumor site, the nanostructures swell due to protonation of the DEAP molecule and then collapse after cleavage of the PLGLAG spacer by MMP‐2, which is overexpressed in the tumor stroma." (PMID 33304763, 2020). "Heavy ion beams can exert anti-tumor effects by upregulating the pro-apoptotic gene BAX and inhibiting the anti-apoptotic gene BCL2, which inhibits MMP2 and MMP9 expression and angiogenesis in tumors." (PMID 33330321, 2020). "Previous studies have identified the critical role of MMP-2 and MMP-9 in tumor invasion and lymph node metastasis of HNSCC." (PMID 32961679, 2020). "Metalloproteinases, specifically MMP-2 and MMP-9, are usually involved in the extracellular matrix disruption that allows tumor cell migration and invasion." (PMID 32158394, 2020). "Inhibition of MMP2/9 significantly increased the CD8+ T cell cytotoxicity and ability to eliminate tumor cells, and the CD8+ T cell cytotoxicity and killing ability was significantly stronger with IFNγ induction, which induced PD-L1 surface expression." (PMID 32988398, 2020). "MMP‐2/9 can decompose most of the substance of ECM, which is beneficial for tumor cells to infiltrate into surrounding normal tissues, and promote tumor proliferation and metastasis." (PMID 32994932, 2020). "In melanoma tumor cells, PI3K plays an important role in the process of VM formation by affecting MMP-2 and MT1-MMP activity." (PMID 32169087, 2020). "There is considerable accumulating evidence suggesting a role of MMP-2, MMP-3, MMP-9 in promoting tumor cell invasion and infiltration." (PMID 33281914, 2020). "Peng & Kopecek (2015) prepared matrix metalloproteinase 2 (MMP-2)-responsive N-(2-hydroxypropyl)- methacrylamide (HPMA) copolymer drugs and tumor penetrating peptide conjugates (P-DOX-PLGLAG-iRGD)." (PMID 33100061, 2020). "MMP2 and MMP9 are gelatinases that are able to degrade and remodel ECM; for these reasons MMP2 and MMP9 play important roles in promoting the metastasis of tumour cells." (PMID 33228670, 2020).
tumor (continued). "WIN-55,212-2 treatment was able to inhibit AKT activation, implicated in survival and migration, as well as downregulate Matrix metalloproteinases-2 (MMP-2) and VEGF-A expression, two extracellular factors involved in tumor invasiveness processes." (PMID 31979368, 2020). "The protein expression of N‐cadherin, vimentin, MMP‐2 and MMP‐9 was also analysed in tumour tissues in our established xenograft model." (PMID 32314545, 2020). "Only MMP2, MMP7 and MMP14 are shown to potentiate tumor growth and/or metastasis in multiple independent papers." (PMID 32325664, 2020). "Meanwhile, CDH11 also shows a robust positive correlation with MMP2, which is one of the notable molecules in the MMP family involved in cell adhesion, angiogenesis, and tumor progression." (PMID 32685527, 2020). "These cells secrete growth factors such as fibroblast growth factor (FGF), VEGF, MMP2, and CXCL-12 chemokine to promote growth, invasion, and metastasis of tumor cells." (PMID 32993787, 2020). "Particularly, MMP-2 and MMP-9,also known as “gelatinases”, destroy the barriers enclosing a tumor, including collagen IV of the basement membrane and the extracellular matrix, allowing invasion into the surrounding tissue." (PMID 32718331, 2020). "During cancer progression, tumor cells induce the expression of MMPs, such as MT1-MMP and MMP-2, which degrade ECM macromolecules like elastin and release EDPs, such as AG-9, that in turns stimulate MMP secretion, leading to an auto-amplification loop." (PMID 33396696, 2020). "Increasing studies showed that both the Rho family and MMP family, including Rac1/2/3, CDC42, RhoA, RhoC, MMP2, and MMP9, are highly expressed in a variety of tumor tissues and are directly correlated with tumor migration and invasion." (PMID 33377649, 2020). "The coculture of THP-1-derived macrophages with GC cells up-regulated CCL5, MMP2, and MMP9 in THP-1 cells, and increased tumor cell proliferation, clonogenic growth and migration." (PMID 32630699, 2020). "MMP-2 and MMP-9 play an important role in tumor development progression by promoting migration and invasion." (PMID 33311443, 2020). "In the present study, compound 9 markedly suppressed the expression of MMP-2 and MMP-9 stimulated by VEGF in HUVECs, indicating that it reduced MMP expression in both ECs and tumor cells." (PMID 32751120, 2020). "The levels of angiogenic growth factor, VEGF, MMP2, and MMP9 secreted into ascites fluid during the growth of EAT cells and tumor cells were reduced in the presence GA or CA as compared to the saline-treated control group mice." (PMID 33261130, 2020). "MMP2 and FN1 genes were analyzed also in tumor cells cultured in 2D and extracted from the xenogeneic masses (mPDGFRα− fraction)." (PMID 33585217, 2020). "In general, a very weak correlation was found between MMP-2 and MMP-9 levels and survival and tumor volume." (PMID 33126765, 2020). "The attracted neutrophils expressed CXCL1 and CXCL8, MMP-2 and MMP-9, thereby inducing tumor angiogenesis and subsequent tumor progression and metastasis." (PMID 32422991, 2020). "Matrix metalloproteinase-2 (MMP-2) and MMP-9 have been shown to play important roles in regulating metastasis and the tumor microenvironment." (PMID 32922544, 2020). "Subsequent studies have shown that an imbalance between MMP-2 and TIMP-2 concentrations in tissues can determine tumor invasion and metastasis." (PMID 32751899, 2020). "MMP-2 on the other hand is critical for tumor angiogenesis and metastasis, and inhibiting MMP-2 hinders tumor progression." (PMID 33411679, 2020). "Highly aggressive tumor cells express high levels of MMPs (MMP-1, MMP-2, and MMP-9), and the 5γ2 chain of laminin." (PMID 32169087, 2020). "The overexpression of oncogenic proteins, such as Cyclin-D1, MCL-1, C-FLIP, XIAP, MMP-9, MMP-2, uPA, and VEGF, are correlated with constitutive NF-κB activity and involved in promoting tumor progression in CRC." (PMID 32429376, 2020).
tumor (continued). "It is clear that PCNA, CyclinD1, MMP2, and MMP9 are downstream effectors of PI3K/AKT pathway involved in tumor invasion and growth." (PMID 33093458, 2020). "To further determine the mechanism of activated fibroblasts on tumor invasion, we performed qRT-PCR to detect the expression levels of five genes (ICAM-1, VEGF-C, MMP2, MMP3, and MMP9) that were reported to be involved in ESCC invasion." (PMID 32637576, 2020). "These embryonic bridging macrophages secrete numerous genes shared by the perivascular macrophages that drive tumor angiogenesis including the angiopoietin receptor, Tek, the VEGF co-receptor Nrp1, growth factors (Fgf2, Pgf) and MMPs (Mmp2, Mmp9)." (PMID 32484158, 2020). "MMP-2 and MMP-9 destroy the basement membrane and degrade the extracellular matrix, promoting tumor invasion." (PMID 32102512, 2020). "26, 27 Moreover, a PC in vivo experiment suggested that salidroside suppressed tumor growth, increased cell apoptosis, inhibited the metastasis of BxPC‐3 cells to the lung, and reduced HIF‐1α, LOXL2, MMP2, and MMP9 while enhanced E‐cadherin in tumor tissue." (PMID 31162697, 2020). "CD147 not only plays a role in lactic acid transportation, but it also can stimulate tumor cells to produce MMPs, specifically MMP-2 and MMP-9, which further promotes tumor invasion and metastasis." (PMID 33178600, 2020). "used a one‐pot synthesis method to conjugate the cytotoxic peptide KLAK, TAT, matrix MMP‐2‐sensitive peptide, and PEG onto dendrimers to obtain PKT‐S‐PEG; the multicellular spheroid showed good tumor penetration." (PMID 33437580, 2020). "MMI-166, a third-generation inhibitor of MMP-2 and MMP-9, has shown to be significantly effective in reducing tumor cell proliferation and the formation of metastasis." (PMID 32392801, 2020). "MMP2, MMP9, VEGF, arginase, and elastase from neutrophil degranulation can also contribute to tumor progression." (PMID 33488669, 2020). "The GlioVis database indicated a significant increase in MMP-2, MMP-14, and MMP-9 mRNA in GBM tumor cells compared to normal tissue." (PMID 33182324, 2020). "After extravasation, MMP-2 and MMP-9 degraded the 100 nm gelatin core NP into smaller 10 nm particles which penetrated deep into tumor tissue via migration through the tumor's ECM." (PMID 33409265, 2020). "In the tumor, the PEG corona was cleaved via MMP-2-mediated degradation of the GPLGLAG peptide spacer, and NLG919 was released via the GSH-mediated reduction of the disulfide bonds." (PMID 32317755, 2020). "It was reported that autophagy was able to secrete some specific factors, such as interleukin-6, MMP-2, and WNT-5A, which was required for tumor cell invasion." (PMID 33004792, 2020). "This is supported by the fact that upregulation of a NDRG3 paralogous, NDRG2, suppresses tumor invasion by inhibiting the matrix metalloproteinases MMP-9 and MMP-2." (PMID 33175867, 2020). "Western blotting results indicated that the protein level of BRD4, c-Myc, CyclinD1, CDK4, MMP-2, MMP-9, Vimentin and N-cadherin were all decreased while E-cadherin was increased in the tumor with circCELSR1 knockdown." (PMID 32640974, 2020). "Evidences also suggest that TAMs promote tumor metastasis through producing matrix metallopeptidase (MMP), such as MMP2, MMP7, and MMP9." (PMID 33201893, 2020). "Firstly, peptides containing anti-tumor agents cisplatin (Pt) and adjudin (ADD) and MMP-2-recognizable sequences were synthesized and then self-assembled into spherical nanoparticles with diameters less than 100 nm." (PMID 32850662, 2020). "Western blot analysis further indicated that inhibition of miR-183-5p led to a down-regulation in the expression of VEGFA, VEGFAR2, ANG2, PIGF, MMP-2 and MMP-9 along with up-regulated FOXO1 expression in tumor tissues (p < 0.05)." (PMID 32364530, 2020). "It is suggested that MMP-2 is related to the degradation of ECM and plays a role in tumor cell growth, differentiation, invasion, metastasis, regulation of tumor angiogenesis and immune surveillance." (PMID 33115469, 2020).
tumor (continued). "Of note, the activities of MMP-9 and MMP-2, the two major metalloproteinases (MMPs) responsible for ECM remodeling and tumor invasion, were significantly lower in the tumor microenvironment of TNFR1 KO mice." (PMID 33202705, 2020). "To validate the results from RNAseq, we measured expression of six genes (COL1A1, FN1, MMP2, TFPI2, CDK6, and CDK4) that were significantly up-regulated in tumor cells compared to normal epithelium by RT-qPCR." (PMID 33142242, 2020). "Consistently, a coexpression analysis of 331 COAD samples using the ChIPBase v2.0 demonstrated a positive relationship between AEBP1 level and the expression of MMP-2, vimentin, TWIST, ZEB1, ZEB2, and SNAIL1, inducers of tumor growth, invasion, and metastasis." (PMID 32565808, 2020). "IGF-1 signals intracellularly through the PI3 and MAPK pathways after binding to IGF-1R on the cell surface, and IGF-1 thereby increases the enzymatic activity of MMP-2 and MMP-9 and enhances the proliferation and migration of tumor cells." (PMID 32972437, 2020). "Our results confirmed that Mmp2 is a downstream regulator of p38 MAPK and its overexpression plays an important role in tumor invasion." (PMID 32790767, 2020). "Further in vitro and in vivo study found that the FOXM1 inhibitor thiostrepton inhibited PTC cell line xenograft tumor growth and this was accompanied by downregulation of FOXM1, MMP9, and MMP2." (PMID 32603365, 2020). "ICAM‐1 expressed on LSECs promoted secretion of IL‐6, prostaglandin E2, VEGF, and MMP2 by tumor cells, which in turn induced VEGFA and MMP2 secretion by HSCs." (PMID 33252863, 2020). "Matrix metalloprotease-2 (MMP-2) and MMP-9 have been reported to induce tumor cell invasion and metastasis formation." (PMID 32984041, 2020). "In the presence of PLGLAG-sensitive MMP-2/9, the PEG layer fell off and the resulting exposure of positive charges promoted the uptake of NPs by the tumor cells." (PMID 32850662, 2020). "Earlier studies in tumor cells also show that MMP-7 is a potential activator of pro-MMP-2, through competitively binding to the TIMP-2 from MMP-2/TIMP-2 complexes, leading to the release of functional MMP-2." (PMID 32630493, 2020). "The main mechanism by which CAFs promote the progression of CCA is to support the proliferation and survival of tumor cells through the expression of cytokines and growth factors, such as periostin, thrombospondin-1, SDF-1, MMP2, MMP9, and IL-1β." (PMID 32539768, 2020). "The results showed that NWXF can down-regulate the expression of Sp1, MMP2, and MMP9 in tumor tissues." (PMID 33329003, 2020). "In turn, stimulated MSCs enhance the expression by cholangiocarcinoma tumor cell lines of CCR5, MMP2 and MMP9, migration, and metastasis formation in tumor xenografts." (PMID 32630699, 2020). "Our results showed that overexpression RIP3 led to significantly decreased MMP-2 and MMP-9 levels, which inhibited the progression of the tumor." (PMID 32984054, 2020). "A few studies have connected matrix metalloproteinases (MMPs), particularly gelatinases (MMP-2 and MMP-9), to tumor angiogenesis and growth." (PMID 30820752, 2020). "Because the main component of extracellular matrix basement membrane is type IV collagen, MMP-2 and MMP-9 play a key role in the degradation of extracellular matrix and promotion of tumor invasion and metastasis." (PMID 31938018, 2020). "Further immunohistochemistry analysis of the dissected tumor tissues showed that MT treatment significantly suppressed the protein expression levels of NF-κB, MMP9, MMP2, and p-AKT." (PMID 32117722, 2020). "In TNBC, brucine, a traditional medicinal herb, was reported to inhibit VM formation in a dose-dependent manner, and downregulate the expression of EphA2, MMP-2, and MMP-9, which are key mediators of tumor invasion, metastasis, and VM formation." (PMID 32169087, 2020).
tumor (continued). "After the MSN-CXB/PTX entered the tumor tissue, CXB was released by the concentrated MMP-2, and the negatively charged nanospheres were converted into positively charged nanospheres, which enhanced internalization." (PMID 33261219, 2020). "Among all MMPs, MMP-1, MMP-2, MMP-3, MMP-7, and MMP-9 are involved in almost all stages of tumor growth, angiogenesis, and metastasis." (PMID 32685465, 2020). "The expression levels of PTEN, MMP2, and MMP9 often indicate invasive and metastatic ability of tumor cells." (PMID 32974191, 2020). "In ESCC, MMP-2 and MMP-9 contribute to tumor invasion and metastasis, and VEGFs including VEGF-A contribute to angiogenesis and are associated with high microvascular density and poor patient prognosis." (PMID 32457351, 2020). "Except for the degeneration of ECM, MMP-2 and MMP-9 also influence the adherence and motility of tumor cells." (PMID 32509341, 2020). "To illustrate the anti-metastatic mechanism of YFTL, we measured E-cadherin, N-cadherin, Vimentin, MMP-2, and MMP-9 expression in tumor and lung tissues of Lewis lung cancer mice by immunohistochemistry and Western blot analysis." (PMID 30781674, 2019). "Both alterations result in increased expression of matrix metalloproteinases including MMP-2 and MMP9 that facilitate degradation of ECM and lead to tumor invasiveness." (PMID 31467533, 2019). "In fact, EVs released by CSCs and undifferentiated tumor cells carry several pro-angiogenic mRNAs, such as VEGF, FGF, angiopoietin 1, ephrin A3, MMP2 and MMP9." (PMID 31013896, 2019). "Like the phosphorylation of YAP principle, NF-κB entry into the nucleus reduced, and thus inhibiting MMP2 and the expression of MMP9 reaches inhibition of tumor cell invasion and metastasis." (PMID 31110076, 2019). "Many studies have sufficiently confirmed that restraining the expression of MMP-2, MMP-9, and VEGFA can inhibit tumor growth, metastasis and angiogenesis." (PMID 31214503, 2019). "effects on cancer cells and tumor growth through activation of such target genes as VEGF, MMP-2 and BCL2." (PMID 31772141, 2019). "On the one hand, fibronectin forms a physical barrier for migrating cells; on the other hand, its interaction with tumor cell integrins, mainly with α5β1, triggers ECM proteolysis through secreting MMP-2 and MMP-9." (PMID 31344926, 2019). "For both MMP2 and COL5A, the mRNA levels in HPV-positive tumor samples were significantly reduced, whereas the levels of CLDN7 were increased." (PMID 30918060, 2019). "Among them, we discovered matrix metalloproteinases, such as MMP-2 and MMP-9, which are widely involved in tumor metastasis." (PMID 30931081, 2019). "Fucoidan, from Cladosiphon novae-caledoniae Kylin, which is consisted of 73% fucose, 12% xylose and mannose, inhibits invasion and tubule formation via the suppression of MMP-2 and -9 activity and downregulation of VEGF expression in tumor cells." (PMID 31781485, 2019). "In other tumour types, ETV5 has been found to mediate EMT through modulation of invasion-related genes, such as NID1, MMP2 and FOXM130,53,54." (PMID 30952872, 2019). "Using zymography, we analyzed the MMP2 and MMP9 content in serum-free medium collected from tumor cells 12 h after the removal of THP1 cells at each co-cultivation step." (PMID 31861801, 2019). "MMP-2 and MMP-9 are members of the matrix metalloproteinase (MMP) family, which play an important role in angiogenesis, wound healing and tumor infiltration." (PMID 31214503, 2019). "Compared with the control group, the tumor tissues from mice in the LOX inhibition group had reduced relative expression levels and enzyme activities of MMP-2 and MMP-9 (P < 0.05)." (PMID 31777578, 2019). "Previous studies have revealed that microRNA-10b promotes the metastasis of a variety of tumor cells by regulating Bim, TFAP2C, P16, P21, E-cadherin, CD138, RHOC, RhoC, uPAR, MMP-2, MMP-9, HOXD10, etc 23-29." (PMID 31592231, 2019).